TTTY4C (testis expressed transcript, Y-linked 4C)
Synonyms: LINC00125; NCRNA00125
Gene: Long non-coding RNA gene on chromosome Y (25,063,083 to 25,099,892, reverse strand). Ensembl gene ENSG00000228296.
Homologues: Paralogues in human: TTTY4 (100% identical), TTTY4B (100% identical).